FOS (Fos proto-oncogene, AP-1 transcription factor subunit)
Diseases named in the same sentence as FOS in open-access papers (continued):
Sharing a sentence is not in itself a finding about the gene and the disease.
cancer (continued). "Importantly, the downregulation of HB-EGF in SCC154 is enough to block the upregulation of JUNB, FOS and FOSB when cancer cells and CAFs are co-cultured." (PMID 39262776, 2024). "However, since the RIP-seq results were also validated with real-time RT-PCR, at least six genes related to “Pathways in cancer,” i.e., TGFB2, CREBBP, EP300, FOS, JUN, and MYC were certainly affected by the hnRNPM-AS1-S interaction." (PMID 37671887, 2023). "This cluster is enriched in the Hippo signaling pathway (KEGG:04390) (Bonferroni-corrected p-value = 1.56e−3), WNT Signaling Pathway (KEGG:04310) (Bonferroni-corrected p-value = 9.57e−3) and Pathways in cancer (KEGG:05200) with genes such as BCL2L1, MYC, FOS (Bonferroni-corrected p-value = 0.047)." (PMID 38057321, 2023). "MAPK10, FOS, and IL-6 genes show extensive low expression in LUSC, BRAC, KICH, and other cancers." (PMID 37666853, 2023). "Moreover, we illustrated downstream‐targeted genes of JUN, FOS, FOSB, EGR1, and ZFP36 and demonstrated that these targeted genes were involved in “positive regulation of cell death”, “pathways in cancer”, “PI3K‐Akt signaling pathway”, and so on." (PMID 35037412, 2022). "Among them, FOS-promoting cell autophagy was upregulated, whereas PI3K (PIK3CA/PIK3CB), which is a key signaling factor in cancer and was found to regulate ABCB1-mediated MDR in our recent study, was downregulated accompanying the remarkable downregulation of ABCB1." (PMID 35459184, 2022). "However, FOS and JUN were significantly downregulated in most of cancer compared to corresponding normal tissues." (PMID 35242279, 2022). "This module included a number of immediate early and growth factor response genes and overlapped with modules previously identified for SDF1 responses in PBs (genes such as CD69 and NR4A2) and growth factor responses in cancer (genes such as EGR1/3, FOS, FOSB, and IER2)." (PMID 36130130, 2022). "We identified ANGPT2 (logFC 3.9, FDR 2.00 × 10−4), APOA1(logFC −4.4, FDR 0.0067), FOS (logFC 1.4, FDR 0.0059) and VEGFA (z-score 2.228, overlap p-value 6.45 × 10−3) as the molecules of interest that have biomarker applications in various cancers." (PMID 35052372, 2021). "Genes related to B and T cell maturation (e.g. CD37, CD79B, JCHAIN, IGLL1, VPREB3, CD52), ribosomal protein genes (RPS-*, RPL-*) and cancer/stress genes (e.g. PRAME, ARHGDIB, FOS, JUN) were within the most significantly deregulated genes between clusters in those samples." (PMID 32415257, 2020). "The results above suggested that EGR1, FOS, and FOSB, three cancer-related TFs, could play an important role in the progression of HCC." (PMID 30228980, 2018). "Collectively these data demonstrate overexpression of EINCR1 leads to defects in the induction of EGF-activated protein coding genes and likely explains the reciprocal relationship between EINCR1 expression and the expression of genes like FOS and FOSB in cancer cells." (PMID 28732076, 2017). "Among identified piRNAs, Hsa_piR_017723_DQ594464 putatively targets FOS, a positive modulator of myeloid differentiation of hematopoietic progenitor; hsa_piR_020814_DQ598650 targets SOX4, an apoptosis regulator in different human cancers." (PMID 26760763, 2016). "Gene ontology, molecular network and canonical pathway analysis of NASP overexpression demonstrated that the most significant changes were in proteins participating in organismal injury, immune response, and cellular growth and cancer pathways (major "hubs": TNF, FOS, EGR1, NFκB, IRF7, STAT1, IL6)." (PMID 19439102, 2009).
cancer (continued). "Therefore, further investigation into the signaling pathways mediated by JUN/FOS and ITGB may offer new directions for developing pan-cancer precision therapies." (PMID 40725477, 2025). "Using qPCR assay for known genes modulated NT157 in other cancer models, we identified that NT157 decreased expression of oncogenes BCL2, CCND1, MYB, and MYC and increased genes related to cellular stress and apoptosis, JUN, BBC3, CDKN1A, CDKN1B, FOS, and EGR1 (all p < 0.05)." (PMID 36224313, 2022). "Indeed, c-FOS was one of the 56 downregulated TFs in OCT4A-KO clone 2-2, indicating its close correlation with OCT4A and the OCT4A-KO-mediated alteration of integrin signaling pathway in somatic cancer cells." (PMID 29789579, 2018). "Genes such as NRAS, SPHK2, FOS, CXCR4, PLD1, GNAI2, and PLA2G4F, and their related biological process terms and pathways, such as apoptosis, MAPK signalling pathway, and cancer signalling pathways, may represent potential targets for OA treatment and diagnosis." (PMID 29968759, 2018). "However, the mechanism of FOS regulation of cancer has not been fully explained." (PMID 36609277, 2023). "Some factors identified (e.g., NF-κB, STAT3, FOS) are known to be involved for transformation in our model, others (e.g., CEBPB, HIF1a, ETS2, FHL2, TCF7L2, and NFE2L2) have been described as oncogenes in other settings, and some proteins (BHLHE40 and MAFB) have not been well linked to cancer." (PMID 29802342, 2018). "In particular, the expression of FOS, FOSB, and ATF3 did not correlate with the low HSF1 levels in these cancer types." (PMID 36010586, 2022). "Most of the NRF2 pathway-related genes showed extensively negative relationships with RNAss; for example, the expressions of FOS, JUN, MAF, MAFK, and PRRT2 in various cancers were negatively related to RNAss." (PMID 35242279, 2022). "In this context, it has been reported that proapoptotic genes, including FOS, FAH, and PRODH, are upregulated in the cancer cells of nonangiogenic NSCLC." (PMID 35267627, 2022). "We also found that exosomes from EBV+ and EBV− cell lines failed to stimulate expression of FOS, c-Myc, and IFNB1, although the exosomes induced significant expression of the ISG IFIT1 in HSC3 cancer cells." (PMID 30389917, 2018). "Promoter occupancy is significantly increased for FOS in the MET model but is decreased in the Non-MET model, relative to the non-cancer model." (PMID 24612742, 2014). "For AP1, ChIP-Seq binding data were available for all three classes (not cancer, MET, and Non-MET cancers), for both FOS and JUN TFs." (PMID 24612742, 2014). "For modules M3, M4, and M5, although the corresponding GO_BP terms were not directly related to cancer, we found PrCa-relevant genes in these three modules, including BTG2, FOS (also known as c-Fos), and CXCR4 in module M3; ARFGAP3 and CDH1 in module M4; and SMAD3 and MXI1 in module M5." (PMID 25418933, 2014). "FOS, JUN and MYBL2 are partly known to play a role in cancer, but not explicitly in MCL." (PMID 18416826, 2008).
infection (124 papers, 2009 to 2026). The state of being infected such as from the introduction of a foreign agent such as serum, vaccine, antigenic substance or organism. "Supplementation with FOS/oligofructose in RCTs was associated with a reduction in the duration of diarrheal days and episodes and with fewer infections." (PMID 39907304, 2025). "In our analysis, genes coding JNK (MAPK8), c-Jun (JUN), and c-Fos (FOS) were all implicated in the subnetwork from the chronic stage of infection, and all showed significantly increased transcript expression levels at this stage." (PMID 28487699, 2017). "There is evidence of two phases of infection from an ‘early’ FOS-linked response to a ‘late’ type II IFN-linked response." (PMID 27228113, 2016). "Additionally, 2 RCTs with “low” to “some” risk of bias assessing the effects of FOS on growth, infection, bowel function, and microbiota were reported separately." (PMID 39907304, 2025). "In the later stages of infection (24 hpi), FHV-1 hijacks host MAPK pathways to promote infection by upregulating FOS." (PMID 39591303, 2024). "The pharmacological inhibition of FOS specifically prevented cell death induced by A. baumannii in cell-based models and led to a reduction of severity in a mouse model of infection." (PMID 39261458, 2024). "Pharmacological inhibition of FOS reduces the cytotoxicity of A. baumannii in cell-based models, and similar results are also observed in a mouse infection model." (PMID 39261458, 2024). "Inhibition of CREB reduced transcript levels below baseline at 30 min post-infection, and abolished M. tb-induced c-FOS levels which peaked at 1h post-infection." (PMID 37000865, 2023). "We identified that T3SS and T6SS affect EGR1 and FOS genes expression in type II pneumocytes during infection." (PMID 35508983, 2022). "We determined that T3SS and T6SS modulate the expression of EGR1, FOS, and numerous genes that are involved in proinflammatory responses in epithelial cells during infection." (PMID 35508983, 2022). "Infection with ZIKV resulted in a significant increase in KLF4 expression as well as a dramatic decrease in FOS transcription." (PMID 35746681, 2022). "Among all DEGs, PRDM1 was the most induced gene (~33-fold higher) after infection, and FOS was the fifth-most-induced gene in this study." (PMID 34578166, 2021). "Using primary human cardiomyocytes (PHCMs), our laboratory demonstrated that T. cruzi induced differential expression of fibrogenic genes during the early phase of infection; these genes include JunB, FOS, EGR1, EGR3 and SNAI1." (PMID 33322418, 2020). "PCC of FOS showed higher values during the acute phase (0.393) compared to the convalescent phase of infection (−0.298)." (PMID 25144185, 2014). "The FOS protein, down regulated in both HP and LP infection, is a leucine zipper protein that dimerize with c-Jun protein to form the AP-1 transcription factor complex." (PMID 24015922, 2013). "coli strain (EPI300-T1R) were generated and NPEC clones FOS 2, FOS 9 and FOS 22 ectopically expressing hemolysin were used for infection experiments." (PMID 22164293, 2011). "Only FOS mRNA expression was increased at 48 hpi compared to mock infection." (PMID 38623540, 2024). "Infection with SARS‐CoV, MERS‐CoV and low pathogenic HCoV‐229E evoked a partially overlapping transcriptional response, characterised by a significant and sustained increase in expression of IEGs such as FOS, NR4A1 and FOSB." (PMID 38623540, 2024). "FOS transcript levels remained high during infection at all later time points." (PMID 38427950, 2024). "Further supporting this hypothesis, the upregulation of an NF-kB signature, including TNFAIP3, NFKBIA and FOS, was also induced in an epithelial cell line model 8 h after infection with SARS-CoV-2." (PMID 37700317, 2023). "Moreover, LCN2/PEPCK/TNFR2 and LIF/FOS showed almost constant up- and down-regulated expression, respectively, across all three infection time-points studied in both groups." (PMID 35234615, 2022).
infection (continued). "Three promising genes (EGR1, JUN and FOS) were eventually identified, and were significantly and differentially expressed in the same breed under different conditions, and in the two breeds after ST infection." (PMID 36557693, 2022). "Next, we investigated the effect of EGR1 and c-FOS on the phagocytosis, the RNA levels of phagocytic receptors mannose receptor (MR) and scavenger receptor (SR) were determined in THP-1 macrophage cells after silencing EGR1 and c-FOS for 24 h, and followed by PA infection for 1 h." (PMID 29487594, 2018). "Knockdown of EGR1 and c-FOS by siRNA transfection suppressed macrophage autophagy before and after PA infection; while overexpression of these two transcription factors enhanced autophagy but reversed the role of BD2 and BD3 on macrophage-mediated PA eradication." (PMID 29487594, 2018). "The increased expression of the FOS gene found in our study indicated a strong stress caused by infection with coagulase-negative and coagulase-negative Staphylococci." (PMID 28587645, 2017). "In both types of infections, caused either by coagulase-positive or coagulase-negative Staphylococci, a marked increase was observed in the expression levels of FOS and TNF genes, and genes encoding the major histocompatibility system proteins (MHC)-BOLA-DQB, BOLA-DRB3, or BOLA-DQA1." (PMID 28587645, 2017). "Conversely, when we performed luciferase assays using a plasmid harbouring the 3’-UTR of FOS and Met mRNAs, in which the binding sites for miR-449a were inactivated by site-directed mutant genesis, the luciferase activity of mutant reporters were unaffected by the simultaneous infection of miR-449a." (PMID 26471185, 2015). "By combining transcriptome analysis and machine learning, we identified four key targets related to VVTT infection in A293 cells: ARC, JUNB, EGR3, and FOS." (PMID 39940969, 2025). "The importance of these results lies in the validation of TFF1, GSTA5, HSPA6, FOS, MPIG6B, F2 and HP not only as key markers for the presence of infection but also for their specificity in differentiating between various Mpox strains." (PMID 39456924, 2024). "Upon infection, a distinct phenotype (subcluster 7.1) emerged among infected cells that shared markers with the highly infected cluster 4, including CITED2, FOS, TXNIP, and CCNG2 genes." (PMID 38896609, 2024). "Components of the JNK and p38 MAPK pathway were induced upon early infection, including the c-Jun N-terminal kinase (JNK) gene MAPK10 as well as the transcription factor AP-1 components FOS, JUN and JUNB." (PMID 38427950, 2024). "Of note, we also detected decreased protein production for c-FOS in CREB inhibited, M. tb infected macrophages at 3h post-infection." (PMID 37000865, 2023). "During infection with the T6SS mutant, the expression of the FOS and EGR1 genes increased in epithelial cells compared to infection with the parental strain." (PMID 35508983, 2022). "Consistent with the results of silencing NbLytB, the FOS-mediated inhibition of IPP biosynthesis in plastids interfered with Bax- and R–Avr interaction-induced PCD and defense responses following pathogen infection." (PMID 36388595, 2022). "This study confirmed the synergistic activity of COL/SUL, COL/FOS, and SUL/FOS combinations in vitro, including checkerboard assay and time-kill assay, and in vivo infection models." (PMID 35794134, 2022). "Here, we found that both colonic and ileal networks generated with CARNIVAL shared similar transcription factors, including ATF2/3, FOS, JUN, STAT1, and NFKB1, which were all upregulated in both tissues upon infection." (PMID 35501398, 2022). "Whereas the signaling pathways enriched in subtype S2 primarily regulated the MAPK signaling pathway and osteoclast differentiation, as well as the infection of virus and E. coli bacteria, targeting the down-regulated TFs, such as NFKB1, FOS, and JUN." (PMID 33777111, 2021).
infection (continued). "We and others showed that during the early phase of cellular infection by T. cruzi, the expression profiles of AP-1 transcription factor network genes including NFATC2, FOS and TGF-β are dysregulated by the parasite." (PMID 33322418, 2020). "DDIT3 can interact with FOS and JUN, hence its induction further suggests activation of apoptosis by infection." (PMID 31664929, 2019). "The expression of 38 genes associated with cell growth and death were significantly up-regulated by ORFV infection at 8 h post-infection, except for CDC25B and FOS." (PMID 28938587, 2017). "For example, TNFSF13B, FOS, POLR3G and PRKCE were down-regulated at 3 h post infection, while ITGB7 and THBD were up-regulated." (PMID 28938587, 2017). "At 7 days after infection, the colony counts in biofilms of control, LIN, FOS, and LIN + FOS groups were 7.46 ± 0.35, 5.97 ± 0.97, 5.26 ± 0.29, and 2.98 ± 0.40 lg cfu/mL, respectively." (PMID 27366751, 2016). "For this pathway, H-Ras, MLC and FOS were significantly modulated by both LPAI- and HPAI-infection; Rho and Gbeta were significantly modulated only by LPAI- or HPAI-infection, respectively." (PMID 24015922, 2013). "In our case we showed that, within CXCR4 signalling pathways, Gβ, H-Ras, Rho, MLC and FOS expressions were modified during early time of LPAI- and/or HPAI-infection." (PMID 24015922, 2013). "In summary, based on 2 RCTs with low to some risk of bias, a statistically significant difference was observed in reducing the number of infections in the short term, but not over an extended duration between the FOS-supplemented and placebo groups." (PMID 39907304, 2025). "Additionally, c-FOS, a subunit of the AP-1 transcription factor, can be induced by EVA71 infection via the endogenous IRES by ITAFs, forming a positive feedback loop that boosts EVA71 replication." (PMID 40869312, 2025). "In transneuronal infection, HSV-2 induces FOS expression in spinal neurons by the fourth day." (PMID 39591303, 2024). "TP63, FOXA1, STAT1, ELK1, FOS, and JUN are TFs in various lung injury or infection types." (PMID 36911695, 2023). "Likewise, B cell differentiation genes (BCL10, CD72, FOS, PTPRC, SH3BP5, PTPN6, etc.)were also downregulated throughout the infection, correlating with the drop of B cell numbers at D8." (PMID 37146079, 2023). "Furthermore, in a ciliated cell line model, a very similar NF-kB-driven transcriptional signature (including NFKBIA, FOS and JUN) has been shown to be specifically induced in SARS-CoV-2-infected cells immediately (< 3 h) post-infection." (PMID 37700317, 2023). "Taken together, these data support the model that the combined actions of VopQ and VopS create a pulse of ERK1/2 MAPK signaling that is restricted to early infection time points, resulting in the controlled expression of downstream transcription factors EGR1 and FOS." (PMID 33563785, 2021). "On the other hand, factors associated with memory development (FOS, KLF6) were upregulated with vaccination but not asymptomatic infection." (PMID 34935643, 2021). "Clear host transcriptional responses could be observed 8 h after infection, including the documented MAPK-based activation of FOS, EGR1, and c-JUN gene expression, in both parental and uS10-KI cells." (PMID 33912921, 2021). "The RNA levels of FOS, and EGR1 were significantly increased as early as 1-day post-infection." (PMID 34545078, 2021). "For example, although the levels of EGR1 and c-FOS were markedly increased shortly after infection, 10 h after infection these proteins were not detectable in lysates of Salmonella infected cells." (PMID 24098123, 2013). "In the same study, infection of moMΦ with Georgia 2007 strain down-regulated other receptors, such as interferon receptors (IFNAR1, IFNAR2, IFNGR) and interleukin receptors (IL4R, IL10RA, IL10RB, and IL17RA), as well as transcriptomic factors (e.g., FOS, JUN, and TBK1)." (PMID 40530033, 2025).